NOX4 (NADPH oxidase 4)
Diseases named in the same sentence as NOX4 in open-access papers (continued):
Sharing a sentence is not in itself a finding about the gene and the disease.
renal fibrosis (continued). "PA reduced the BP, RAAS, inflammation and cytokines, promoted the urine, and relieved renal pathological injury and collagen deposition, repaired renal fibrosis, decreased the expression of NADPH Oxidase 4 (NOX4), transforming growth factor-β (TGF-β), SMAD3 and MAPK signaling pathway in SHR rats." (PMID 37353787, 2023). "Among pro-oxidant enzymes, NOX4 is known as a key player in renal fibrosis." (PMID 36661510, 2023). "Inhibition of BRD4 attenuated renal fibrosis by blocking TGF-β-mediated Nox4 expression." (PMID 37737256, 2023). "The mechanism of the role of ROS in the formation of renal fibrosis can be interpreted as follows: High glucose induces the increased expression of NADPH oxidase 4 (NOX4), contributing to the overproduction of ROS, which activates the TGF-β/Smads pathway and other pro-fibrotic factors." (PMID 36601125, 2022). "NOX4 is a main source of ROS in the kidney and plays an important role in renal fibrosis." (PMID 36552549, 2022). "In the study of renal disease, it was found that RhoA/ROCK1 is the upstream signal molecule of NOX4/ROS, and the activation of the RhoA/ROCK1 signal pathway can upregulate the expression of NOX4/ROS, promote the differentiation of renal myofibroblasts, and aggravate renal fibrosis." (PMID 34135982, 2021). "NOX4 is highly expressed in the tubular cell compartment, and its upregulation may promote renal oxidative stress and renal fibrosis." (PMID 30993112, 2019). "NADPH oxidase Nox4-derived reactive oxygen species (ROS) play important roles in renal fibrosis." (PMID 28805491, 2017). "It has been reported that Nox4 is the main source of ROS in the kidneys during renal fibrosis." (PMID 28805491, 2017). "Resveratrol, an anti-inflammatory and antioxidant polyphenol, inhibits renal fibrosis via the activation of SIRT1 and deacetylation of SMAD3 in UUO mice, and decreases the renal fibrosis caused by diabetic hyperglycemia activated renal fibroblasts via the inhibition of AMPK/NOX4/ROS signaling." (PMID 33163486, 2020). "A subsequent study showed that HK-2 cells exposed to IL-1β strongly expressed TXNIP, NADPH oxidase 4 (Nox4), and ROS, indicating that inhibition of NLRP3 inflammasome activation suppresses renal fibrosis." (PMID 37500614, 2023). "Renal fibroblasts play a dominant role in the renal fibrosis and they responded to ADMA with the increase in the intracellular ROS generation through NOX-4." (PMID 32994511, 2020). "From these findings, we demonstrate holistically that ADMA activates NOX-4, which is an upstream activator of ERK1/2 signaling cascade, leading to renal fibrosis." (PMID 32994511, 2020). "Despite the evidence of the role of NOX-4 and ERK pathway in renal fibrosis, little is known about their interactions with COX-2." (PMID 31396082, 2019). "Dysregulated mitochondrial apoptosis, increased activity of NOX4 and XOR, and low levels of NO not only result from ROS production but also stimulate greater ROS production, leading to inflammation, tubular injury, renal fibrosis, and endothelial injury." (PMID 39456439, 2024). "Recent evidence revealed that complanatoside A inhibits NOX4-mediated NLRP3 inflammasome activation and oxidative stress, indicating that complanatoside A could be used to treat renal fibrosis." (PMID 37500614, 2023). "QYYY granules can also counter renal fibrosis by inhibiting the production of TGF-β, regulating the AngII-AT1R-CTGF pathway, and repressing the NF-κB inflammation pathway and the expression of NOX4." (PMID 34484396, 2021). "Interestingly, in renal fibrosis, RhoA/ROCK1 aggravates renal fibrosis by activating the NOX4/ROS signalling pathway." (PMID 32496208, 2020). "In particular, an increased NOX-4 expression in renal cells was discovered in streptozotocin-induced diabetic rats, and subsequent studies have argued that up-regulated NOX-4 is the primary source of the increased ROS production in the kidneys that contributes to renal fibrosis and DNF." (PMID 36979960, 2023).
renal fibrosis (continued). "This is consistent with previous studies, where the silencing of NOX5 in human mesangial cells but not NOX4 led to the attenuation of high-glucose-induced upregulation of these markers of fibrosis, further highlighting the dominant role of NOX5 in exacerbating renal fibrosis in DKD." (PMID 38671844, 2024).
Stroke (43 papers, 2010 to 2025). Sudden impairment of blood flow to a part of the brain due to occlusion or rupture of an artery to the brain. "Similar to the reports in the pressure-overloaded heart, NOX4 has been linked to the pathophysiology of stroke, since its expression and activity is increased as a consequence of hypoxia." (PMID 32923955, 2019). "Nox4 had been reported to be implicated in animal models of cerebral ischemia and reperfusion injury after stroke." (PMID 31329158, 2019). "Nox4 derived oxidative stress is also considered as relevant pathomechanism of stroke, a leading cause of death and disability." (PMID 29538284, 2018). "She reported on stroke outcome in mice conditionally deficient for NOX4 in endothelial or smooth muscle cells thereby extending the already published data on constitutive Nox4−/− mice." (PMID 24330587, 2013). "These details indicate both the strong specificity and universality of NOX4 deficiency in protecting against stroke-mediated brain damage." (PMID 20877473, 2010). "Next we sought to elucidate the underlying mechanisms of this NOX4-specific neurotoxicity in stroke." (PMID 20877715, 2010). "Strikingly, the group found that NOX4-deficient mice exhibited a smaller extent of tissue death, experienced less severe neurological deficits, and survived for longer after stroke than did wild-type mice." (PMID 20877473, 2010). "This protection in Nox4−/− mice was further underlined by a significantly reduced post-stroke long-term mortality." (PMID 20877715, 2010). "The continuous administration of antihypertensive medication may help mitigate functional impairment caused by stroke by inhibiting NOX4 expression." (PMID 39334724, 2024). "We then validate this approach by comparing classical biased KH gene selection for brain hypoxia to a de novo identified highly stable HK panel and their reliability in reproducing the discovery of Nox4 as a key inducible gene with a causal role in post-stroke neurodegeneration." (PMID 35853974, 2022). "More selective targeting of NOX4 is an important direction of stroke-associated researches." (PMID 35154560, 2022). "We found that NOX4 causes oxidative stress and death of nerve cells after a stroke." (PMID 20877715, 2010). "Furthermore, while elevated ROS levels, ROS-damaged proteins, and neuronal cellular suicide were quite evident in the brains of post-stroke wild-type mice, NOX4-deficient mice displayed much lower levels of all these indicators." (PMID 20877473, 2010). "NOX4 deficiency also correlated with reduced fluid flooding in brain regions adjacent to the stroke, which the authors suggest could be related to decreased damage and leakiness of brain blood vessels." (PMID 20877473, 2010). "Indeed, in NOX4 knockout (NOX4−/−) mouse models, where other NOX isoforms remained, the absence of NOX4 conferred protection against oxidative stress and was associated with reduced neuronal apoptosis following stroke, highlighting NOX4′s role in neuronal damage under oxidative stress conditions." (PMID 40227195, 2025). "However, the protective role of NOX4 may differ from its role in the brain where NOX4 has been shown to contribute to OS and the neurodegeneration linked to stroke and other pathological conditions." (PMID 29165383, 2017). "For instance, NOX4 plays a significant role in oxidative stress and neuronal injury, making it a potential therapeutic target for stroke and related conditions." (PMID 40227195, 2025). "Electroacupuncture preconditioning, targeting NOX4, demonstrated protective effects on blood–brain barrier (BBB) integrity and reduced oxidative stress, emphasizing the potential of NOX4 inhibition in stroke interventions." (PMID 39334724, 2024). "The study demonstrates that olmesartan administration, both before and after stroke onset, significantly contributes to the recovery process by reducing cell death and oxidative stress through NOX4 inhibition." (PMID 39334724, 2024).
Stroke (continued). "Significantly, the expression of NOX2 mRNA was also increased substantially through the initial 7 days, whereas NOX4 mRNA levels increased from day 7 to day 28 post-stroke." (PMID 39334724, 2024). "The role of NOX2 and NOX4 in promoting angiogenesis and neovascularization after stroke involves the activation of NOX2 and NOX4, which increases the production of ROS." (PMID 39334724, 2024). "Findings from two critical studies have revealed that the temporal and spatial dynamics of post-stroke NOX2 and NOX4 expression are associated with vascular remodeling and recovery." (PMID 39334724, 2024). "In a NOX4 KO model of stroke, smaller infarct volumes and neuroprotection were observed along with a reduction in the disruption of the blood–brain barrier, although inflammatory cell infiltration was not assessed." (PMID 36897852, 2023). "When applying these genes to normalise expression levels of the validated stroke target gene, inducible Nox4, we obtained opposing results." (PMID 35853974, 2022). "There was a trend toward an increased expression of NOX4 in oxygen and glucose depletion/reoxygenation (OGD/R)-treated human brain vascular endothelial cells collected after AS-associated stroke." (PMID 33744854, 2021). "Our data, obtained using a murine stroke model with the POC targeted against NOX4 for the amelioration of stroke is an example of efficacious gene knockdown in a model of a disease resident in the brain in which the BBB is intact." (PMID 33869275, 2021). "The gene, NOX4, has been shown to be upregulated during stroke and thus NOX4 offers a convenient target to test the therapeutic effects of a MTfp-delivered siRNA." (PMID 33869275, 2021). "In vivo studies reported increased levels of Nox4 protein in cerebral endothelial cells from mouse ischemic brains and stroke patient samples." (PMID 32630636, 2020). "Here, our data highlighting the capacity of polyphenols to target both Nox4 and NFκB suggest the relevance to assess their possible benefits in in vivo animal models exposed to cerebrovascular complications, such as stroke." (PMID 32630636, 2020). "In contrast to the acute injury model of stroke, aging is a slow process, and there was a compensatory increase in Nox4 expression in the aging Nox2KO brain." (PMID 31329158, 2019). "Nox4−/− mice were protected from oxidative stress, blood–brain barrier leakage, and neuronal apoptosis in a stroke model, indicating a pathological role of Nox4 in this model." (PMID 30334629, 2019). "Attenuating poststroke neurodegeneration by Nox4 inhibition has been proposed as a new concept in stroke therapy." (PMID 29538284, 2018). "The overexpression of NOX2 and NOX4 after stroke has been associated with aggravated ischemic injury, and the stroke size was reduced in NOX2- and NOX4-deficient mice." (PMID 29849881, 2018). "NOX2 and NOX4 overexpression is associated with aggravated ischemic injury, while NOX2/4-deficient mice had reduced stroke size." (PMID 29849881, 2018). "Genetic absence or pharmacological inhibition of functional NADPH oxidases, especially NOX2 and NOX4, reduces brain tissue damage and improves neurological outcome following experimental stroke." (PMID 26941888, 2016). "Limitations in the available antibodies to specifically label the Nox4 isoform, or prevent its activity, mean that the search for a reliable tool with which to characterise the role of Nox4 in stroke injury is underway." (PMID 24961415, 2013). "Elevated Nox4 levels were detectable as early as 24 h after stroke, reaching a peak between 7 and 15 days and persisting for up to 30 days, indicating a role for Nox4 in stroke progression and recovery." (PMID 24961415, 2013). "Subsequently, we showed that Nox4 was also elevated immediately after stroke and reperfusion in rats, but only at 6 h after stroke." (PMID 24961415, 2013).
Stroke (continued). "Our findings show increased temporal expression for both Nox2 and Nox4 NADPH oxidase mRNA in the long term recovery phase of stroke concurrently with increased angiogenesis within the damaged brain." (PMID 24961316, 2013). "We have reported that Nox4 is also up-regulated in the damaged rat brain in the weeks after stroke, in addition to up-regulation of Nox2 and the most important pro-angiogenic factor, VEGF." (PMID 24961415, 2013). "VEGF mRNA expression was increased in the ipsilateral cortex and striatum between 6 h and 28 days post-stroke concurrently with a marked increase in Nox2 mRNA expression up to 7 days, and increased Nox4 mRNA expression detected between 7 and 28 days." (PMID 24961316, 2013). "Whilst the interpretation of the stroke data obtained with NOX4 KO mice is straightforward and was recently confirmed in a tgNOX4 model of brain ischemia showing larger infarct sizes, the pressure overload and lung data are less so." (PMID 22648375, 2012). "While, there is much evidence to support a role for Nox4 in stroke and other diseases, controversy is unfortunately the most consistent theme throughout." (PMID 23125837, 2012). "As for NOX2, the spatiotemporal profile of NOX4 mRNA expression after stroke in rats has been measured." (PMID 22625431, 2012). "Here, NOX4 expression was also validated at the protein level (by immunohistochemistry) in brain samples from stroke patients and in mouse brain slices." (PMID 22625431, 2012). "This study shows that NOX4 seems to play a major role in brain damage and thus is a promising target in stroke therapy." (PMID 22625431, 2012). "Because NOX4 mRNA is expressed at higher levels in cerebral than in peripheral blood vessels and is induced in stroke, we first sought to validate these data not only at the mRNA but also at the protein level." (PMID 20877715, 2010). "Here we identify NOX4 as a relevant molecular source of oxidative stress in cerebral ischemia, including some cases of human stroke." (PMID 20877715, 2010). "NOX4 is the most abundant vascular isoform; its expression is even higher in cerebral than in peripheral blood vessels and, further, induced in stroke." (PMID 20877715, 2010). "Although NOX4 was barely detectable in healthy brain regions, clear positive labeling of NOX4 was seen in neurons and vascular endothelial cells from the forebrain cortex of stroke patients." (PMID 20877715, 2010). "The identification of NOX4 as a major source of oxidative stress in stroke and demonstration of dramatic protection after stroke in mice by NOX4 deletion or NOX inhibition, opens up new avenues for treatment." (PMID 20877715, 2010). "NOX4 therefore represents a major source of oxidative stress and novel class of drug target for stroke therapy." (PMID 20877715, 2010). "NOX4 thus represents a most promising new therapeutic target for reducing oxidative stress in general, and in brain injury due to stroke in particular." (PMID 20877715, 2010). "Similarly, NOX2 and NOX4 positively contribute to vascular remodeling after stroke, whereas NOX1 is recognized as a key regulator of oxidative damage in post-stroke neurogenesis, with its modulation being associated with improved functional recovery." (PMID 39334724, 2024). "Among seven known NOX subtypes, NOX1-5 and dual oxidase (DUOX) 1/2, NADPH oxidase 4 (NOX4) is one of the most extensively distributed isoforms in the central nervous system and has been characterized in different diseases, such as stroke, trauma, tumors and neurodegenerative diseases." (PMID 37907746, 2023). "In addition, expression of NOX1, NOX2, and NOX4 significantly increases in brain tissue and the cerebral vasculature after stroke, and these enzymes are a substantial source of pathological ROS following intracerebral hemorrhage." (PMID 36793787, 2023). "Likewise, NOX4 knockdown enhanced neuronal tolerance to oxidative stress, curbed ROS production, and dampened neuronal cell death in a rodent model of stroke." (PMID 37375795, 2023).